TGM6 (transglutaminase 6)
Description:
Catalyzes the cross-linking of proteins and the conjugation of polyamines to proteins.
Synonyms: TGY; TG6; TGM3L; dJ734P14.3; SCA35
Tractability: Small molecule: it belongs to a druggable protein family. PROTAC: a small molecule that binds it is known.
Target class: Protein-glutamine glutamyl-transferase; Enzyme; Aminoacyltransferase
Gene: Protein-coding gene on chromosome 20 (2,380,901 to 2,432,753, forward strand). Ensembl gene ENSG00000166948.
Subcellular location: Cytoplasm
Gene Ontology:
Molecular function: protein-glutamine gamma-glutamyltransferase activity
Biological process: peptide cross-linking
Cellular component: cytoplasm
Genetic constraint (gnomAD): Loss-of-function variants: 74 observed, 79.18 expected, observed/expected ratio (o/e) 0.93, 90% interval 0.77 to 1.13. The upper end of that interval is the gene's LOEUF score, 1.13, which puts it in group 4 of 6, group 1 being the genes least tolerant of losing a copy. Missense variants: 968 observed, 974 expected, observed/expected ratio (o/e) 0.99, 90% interval 0.94 to 1.05. Synonymous variants: 383 observed, 392.82 expected, observed/expected ratio (o/e) 0.98, 90% interval 0.9 to 1.06.
Homologues: Orthologues: chimpanzee TGM6 (98% identical), macaque TGM6 (96% identical), pig TGM6 (87% identical), dog TGM6 (86% identical), mouse Tgm6 (86% identical), rat Tgm6 (85% identical), guinea pig TGM6 (84% identical), rabbit TGM6 (81% identical), tropical clawed frog tgm3l.8 (42% identical), tropical clawed frog tgm6 (41% identical), tropical clawed frog tgm3l.2 (40% identical), tropical clawed frog tgm3l.7 (40% identical), and 2 more. Paralogues in human: TGM3 (50% identical), TGM5 (47% identical), TGM7 (44% identical), TGM2 (41% identical), TGM1 (37% identical), F13A1 (34% identical), TGM4 (33% identical), EPB42 (30% identical).
Diseases named in the same sentence as TGM6 in open-access papers:
TGM6 is named in the same sentence as 48 diseases in open-access papers, as found by Europe PMC text mining. Sharing a sentence is not in itself a finding about the gene and the disease. The quoted sentences say what the papers report.
Ataxia (13 papers, 2010 to 2026). Ataxia refers to impaired coordination of voluntary muscle movement. "Mutations in Transglutaminase 6 (TG6) have been linked to a genetic form of spinocerebellar ataxia, namely SCA35." (PMID 42241495, 2026).
celiac disease (9 papers, 2013 to 2024). An autoimmune genetic disorder with an unknown pattern of inheritance that primarily affects the digestive tract. "Investigations of these manifestations in celiac disease have identified a number of associated immune abnormalities, including B cell reactivity towards various autoantigens, such as transglutaminase 3, transglutaminase 6, synapsin I, gangliosides, and collagen." (PMID 30127251, 2018).
dermatitis herpetiformis (6 papers, 2010 to 2020). "Transglutaminase 6 (TG6), a member of the Transglutaminase family of protein-crosslinking enzymes and is closely linked to TG2 (the autoantigen in CD) and Transglutaminase 3 (TG3, the autoantigen in dermatitis herpetiformis)." (PMID 32244870, 2020).
spinocerebellar ataxia type 35 (6 papers, 2018 to 2025). Spinocerebellar ataxia type 35 (SCA35) is a subtype of autosomal dominant cerebellar ataxia type 1 (ADCA type 1) characterized by the adult-onset of progressive gait and limb ataxia, dysarthria, ocular dysmetria, intention tremor, hyperreflexia and spasmodic torticollis. "Gluten ataxia is often associated with Spinocerebellar ataxia type 35 with mutation in the Transglutaminases (TGM6) gene or autoantibodies against TGM6." (PMID 39339713, 2024). "Mutations in TGM6 are associated with spinocerebellar ataxia type 35, one of a group of genetic disorders characterized by poor coordination of hands, gait, speech, and eye movements as well as frequent atrophy of the cerebellum." (PMID 30973874, 2019). "Recently, missense mutations in the of transglutaminase 6 gene have been identified in families of Chinese patients with spinocerebellar ataxia type 35 (SCA35)." (PMID 30127251, 2018). "Heterozygous mutations in the TGM6 gene located on chromosome 20p13 have been reported to cause autosomal dominant spinocerebellar ataxia type 35 (SCA35)." (PMID 40731814, 2025). "In line with this last group, spinocerebellar ataxia type 35 (SCA35) results from missense mutations in TGM6, as found by Wang and colleagues by combining exome sequencing and linkage analysis in four probands of a Chinese family." (PMID 33160304, 2020). "While TGM6 variants have been linked to PD and spinocerebellar ataxia type 35, their role in ET or ET preceding PD has not yet been documented." (PMID 40731814, 2025).
Autoimmunity (5 papers, 2013 to 2025). The occurrence of an immune reaction against the organism's own cells or tissues. "Gluten ataxia (GA) is the primary neurological manifestation of gluten sensitivity, characterised by loss of Purkinje cells throughout the cerebellar cortex and rooted in autoimmunity to transglutaminase 6 (TG6)." (PMID 40172737, 2025). "Within humoral autoimmunity to neuronal antigens, anti-transglutaminase 2- or transglutaminase 6-related immunoglobulin depositions have been identified not only in the gut but also in the cerebellum, pons, medulla and around brain blood vessels." (PMID 25062250, 2014).
amyotrophic lateral sclerosis (2 papers, 2017 to 2025). Amyotrophic lateral sclerosis (ALS) is a neurodegenerative disease characterized by progressive muscular paralysis reflecting degeneration of motor neurons in the primary motor cortex, corticospinal tracts, brainstem and spinal cord. "Interestingly, an abnormality in central motor circuits has been suggested by previous studies reporting an association between CD and motor neuron diseases; moreover, some researchers found transglutaminase-6 antibodies in the serum of patients with amyotrophic lateral sclerosis." (PMID 28489931, 2017).
Brain atrophy (1 paper, 2021). Partial or complete wasting (loss) of brain tissue that was once present. "There is, however, recent evidence to suggest that the presence of IgA anti-transglutaminase 6 (TG6) antibodies has a significant link to brain atrophy in patients with CD." (PMID 34984152, 2021).
colon cancer (1 paper, 2019). "Further studies are still needed to explore the biological functions and underlying molecular mechanisms of REG1B, TGM6, NTF4, PNMA5, and HOXC13 in colon cancer." (PMID 30884206, 2019). "The prognostic signature based on REG1B, TGM6, NTF4, PNMA5, and HOXC13 could divide colon cancer patients into high–risk and low–risk groups, with an AUC of the ROC of 0.771." (PMID 30884206, 2019). "We then constructed a prognostic signature based on the expression of REG1B, TGM6, NTF4, PNMA5, and HOXC13 which could provide significant prognostic value for colon cancer." (PMID 30884206, 2019). "Using these data, we constructed a prognostic signature based on the expression of REG1B, TGM6, NTF4, PNMA5, and HOXC13 which could provide great significant prognostic value for colon cancer." (PMID 30884206, 2019).
gastric cancer (1 paper, 2020). A primary or metastatic malignant neoplasm involving the stomach. "In contrast, other transglutaminases including TGM1, TGM4, TGM5, TGM6, and TGM7 exhibited a significant decrease in gene expression in the gastric cancer tissue samples." (PMID 32467608, 2020).
heart failure (1 paper, 2024). Inability of the heart to pump blood at an adequate rate to meet tissue metabolic requirements.
psoriasis (1 paper, 2021). An autoimmune condition characterized by red, well-delineated plaques with silvery scales that are usually on the extensor surfaces and scalp. "Importantly, CXCL9 and SPRR1B, as well as methylation markers TGM6 and S100A9, have an impact on the risk of psoriasis." (PMID 34134787, 2021). "Nomogram showed that TGM6 and S100A9 may be associated with an increased risk of psoriasis." (PMID 34134787, 2021). "CXCL9, SPRR1B, TGM6 and S100A9 may be potential targets for the diagnosis and treatment of psoriasis." (PMID 34134787, 2021).
pulmonary TB (1 paper, 2018). "Moreover, we determine that the rs6114027 risk allele is related to decreased TGM6 transcripts in PBMCs from pulmonary TB patients and severer pulmonary TB disease." (PMID 30287856, 2018).
neurological disorders (9 papers, 2014 to 2025). "However, recent studies have highlighted the potential role of circulating autoantibodies to Transglutaminase 6 in predisposed individuals to neurological disorders, including headaches." (PMID 38731144, 2024). "The evidence suggests that TGM6 plays an important role in neurologic diseases; however, the exact mechanism of action remains elusive." (PMID 30287856, 2018). "Recently it has been discovered that corresponding circulating antibodies against transglutaminase 6 (TG6) may play a role in particular gluten-related neurological disorders." (PMID 24982802, 2014). "There is some debate whether TGM6 variants are causative for ATX‐TGM6 (SCA35), as benign or low penetrant variants might be misclassified as pathogenic and therefore, might also occur in patients with various neurologic diseases or normal controls." (PMID 37332650, 2023). "Autoantibodies directed against transglutaminase 6 (TG6)—an enzyme integral to protein cross-linking—have been detected predominantly in the CSF of individuals with SPMS and PPMS, in contrast to patients with RRMS and other non-MS neurological diseases." (PMID 41226806, 2025).
cancer (3 papers, 2019 to 2025). A tumor composed of atypical neoplastic, often pleomorphic cells that invade other tissues. "However, TGM3, an important paralog of TGM6, has been studied in cancer." (PMID 30884206, 2019).
peripheral neuropathy (2 papers, 2020 to 2025). A disorder affecting the peripheral nervous system. "Gluten sensitivity, as marked by detected antibodies against transglutaminase 6 in the sera of patients, commonly leads to peripheral neuropathy." (PMID 40149665, 2025).
tumor (1 paper, 2022). "In addition, TGM4, TGM6, and TGM7 genes were the lowest expressed and did not exhibit statistically significant differences in the level of expression between tumor and healthy tissues." (PMID 35725560, 2022).
TGM6 also shares sentences with these, for which no sentence is quoted: enteropathy (4 papers); epilepsy (3); Huntington disease (3); cerebellar ataxia (2); cerebral palsy (2); Lupus (2); Parkinson disease (2); acral peeling skin syndrome (1); acute myeloid leukemia (1); adenocarcinoma (1); Alzheimer disease (1); autoimmune neuropathy (1); autosomal dominant disease (1); autosomal dominant spinocerebellar Ataxia (1); autosomal recessive congenital ichthyosis (1); bleeding disorders (1); breast carcinoma (1); cerebellar degeneration (1); COVID-19 (1); genetic disorders (1); ischemic stroke (1); melanoma (1); motor neuron diseases (1); movement disorder (1); multiple sclerosis (1); Myelopathy (1); neurodegenerative disease (1); obsessive-compulsive disorder (1); Restless Leg Syndrome (1); Stroke (1).
A further 2 diseases each share a sentence with TGM6 in 1 paper.